ENSG00000263809 (novel protein)
Gene: Protein-coding gene on chromosome 17 (8,368,638 to 8,383,187, reverse strand). Ensembl gene ENSG00000263809.
Genetic constraint (gnomAD): Missense variants: 52 observed, 103.94 expected, observed/expected ratio (o/e) 0.5, 90% interval 0.4 to 0.63. Synonymous variants: 33 observed, 34.71 expected, observed/expected ratio (o/e) 0.95, 90% interval 0.72 to 1.27.